FBXW8 (F-box and WD repeat domain containing 8)
Description:
Substrate-recognition component of the Cul7-RING(FBXW8) ubiquitin ligase complex, which mediates the ubiquitination and subsequent proteasomal degradation of target proteins. The Cul7-RING(FBXW8) complex mediates ubiquitination and consequent degradation of GORASP1, acting as a component of the ubiquitin ligase pathway that regulates Golgi morphogenesis and dendrite patterning in brain. Mediates ubiquitination and degradation of IRS1 in a mTOR-dependent manner: the Cul7-RING(FBXW8) complex recognizes and binds IRS1 previously phosphorylated by S6 kinase (RPS6KB1 or RPS6KB2). The Cul7-RING(FBXW8) complex also mediates ubiquitination of MAP4K1/HPK1: recognizes and binds autophosphorylated MAP4K1/HPK1, leading to its degradation, thereby affecting cell proliferation and differentiation. The Cul7-RING(FBXW8) complex also mediates ubiquitination of phosphorylated cyclin-D1 (CCND1). The Cul7-RING(FBXW8) complex is however not a major regulator of CCND1 stability during the G1/S transition (By similarity). Associated component of the 3M complex, suggesting that it mediates some of 3M complex functions.
Synonyms: FBW6; FBW8; FBX29; FBXO29; FBXW6
Tractability: PROTAC: ubiquitination databases record sites on it.
Gene: Protein-coding gene on chromosome 12 (116,910,839 to 117,032,498, forward strand). Ensembl gene ENSG00000174989.
Subcellular location: Cytoplasm, perinuclear region; Golgi apparatus; Cytoplasm
Subcellular location (Human Protein Atlas): Cytosol
Pathways (Reactome):
Immune System: Antigen processing: Ubiquitination & Proteasome degradation
Metabolism of proteins: Neddylation
Gene Ontology:
Molecular function: protein binding; ubiquitin-like ligase-substrate adaptor activity
Biological process: cell population proliferation; Golgi organization; negative regulation of insulin receptor signaling pathway; positive regulation of dendrite morphogenesis; proteasome-mediated ubiquitin-dependent protein catabolic process; protein ubiquitination; ubiquitin-dependent protein catabolic process; cilium assembly; SCF-dependent proteasomal ubiquitin-dependent protein catabolic process; positive regulation of proteasomal ubiquitin-dependent protein catabolic process
Cellular component: 3M complex; Cul7-RING ubiquitin ligase complex; cytoplasm; cytosol; Golgi apparatus; perinuclear region of cytoplasm; centriole; ciliary basal body; SCF ubiquitin ligase complex
Genetic constraint (gnomAD): Loss-of-function variants: 50 observed, 52.59 expected, observed/expected ratio (o/e) 0.95, 90% interval 0.76 to 1.2. The upper end of that interval is the gene's LOEUF score, 1.2, which puts it in group 5 of 6, group 1 being the genes least tolerant of losing a copy. Missense variants: 682 observed, 678.4 expected, observed/expected ratio (o/e) 1.01, 90% interval 0.94 to 1.07. Synonymous variants: 280 observed, 272.87 expected, observed/expected ratio (o/e) 1.03, 90% interval 0.93 to 1.13.
Homologues: Orthologues: chimpanzee FBXW8 (99% identical), macaque FBXW8 (98% identical), dog FBXW8 (86% identical), rabbit FBXW8 (84% identical), guinea pig FBXW8 (79% identical), pig FBXW8 (79% identical), mouse Fbxw8 (79% identical), rat Fbxw8 (78% identical), tropical clawed frog fbxw8 (48% identical), zebrafish fbxw8 (42% identical). Paralogues in human: WDR64 (13% identical), FBXW7 (12% identical), FBXW11 (12% identical), BTRC (11% identical), EFCAB8 (11% identical), TRAF7 (11% identical), WDR49 (10% identical), WDR86 (9% identical), FBXW9 (7% identical), WDR54 (7% identical), FBXW12 (6% identical), PAAF1 (5% identical), and 2 more.
Diseases named in the same sentence as FBXW8 in open-access papers:
FBXW8 is named in the same sentence as 12 diseases in open-access papers, as found by Europe PMC text mining. Sharing a sentence is not in itself a finding about the gene and the disease. The quoted sentences say what the papers report.
3-M syndrome (2 papers, 2015 to 2022). 3M syndrome is a primordial growth disorder characterized by low birth weight, reduced birth length, severe postnatal growth restriction, a spectrum of minor anomalies (including facial dysmorphism) and normal intelligence. "However, the vertebrate-specific CRL7FBXW8 is of interest because it eludes existing models, yet its constituent cullin CUL7 and F-box protein FBXW8 are essential for development, and CUL7 mutations cause 3M syndrome." (PMID 35982156, 2022). "Thus, although FBXW8 has not been found to be mutated in 3M syndrome patients, the CUL7 mutations at the interface with FBXW8 may suggest a role in the function of the 3M E3 ligase complex." (PMID 35982156, 2022). "And if so, are there essential functions of FBXW8 explaining lack of disease mutations, and by extension does CUL1 also play a role in 3M syndrome?" (PMID 35982156, 2022).
choriocarcinoma (2 papers, 2022 to 2025). An aggressive malignant tumor arising from trophoblastic cells. "FBXW8 has been identified as a direct target of miR-218 and is implicated in MALAT1-mediated promotion of choriocarcinoma cell proliferation." (PMID 40534867, 2025). "FBXW8 plays a role in regulating cell growth and cell cycle progression in choriocarcinoma, with its overexpression exerting opposing effects on these processes." (PMID 40534867, 2025). "One study reported that miR-218 suppressed the cell proliferation via inhibition of FBXW8 in choriocarcinoma JEG-3 cells." (PMID 35928868, 2022). "Thus, MALAT1 enhances cell proliferation by interacting with miR-218 and upregulating FBXW8, highlighting a critical regulatory axis in choriocarcinoma progression." (PMID 40534867, 2025). "Hence, MALAT1 promoted cell proliferation via interaction with miR-218 and upregulation of FBXW8 in choriocarcinoma." (PMID 35928868, 2022). "FBXW8 has been reported to involve in cell growth and cell cycle progression in choriocarcinoma." (PMID 35928868, 2022). "What is more, FBXW8 was found to be a direct target of miR-218 and was involved in MALAT1-meidiated promotion of cell proliferation in choriocarcinoma." (PMID 35928868, 2022).
colorectal cancer (2 papers, 2021 to 2022). A primary or metastatic malignant neoplasm that affects the colon or rectum. "Also, decreased levels of uc.77– promote colorectal cancer proliferation by inhibiting FBXW8-mediated CDK4 degradation, while uc.63+ induces gastric cancer progression via NF-κB signaling." (PMID 36214222, 2022).
intrauterine growth restriction (1 paper, 2021). "FBXW8 gene was associated with fetal programming in a study that analyzed intrauterine growth restriction." (PMID 34887899, 2021).
ovarian carcinoma (1 paper, 2017). A malignant neoplasm originating from the surface ovarian epithelium. "For instance, FBXW8, a gene with reported nonsense and splicing mutations, is a differentially expressed hub connecting a number of Class II genes in our ovarian cancer PIE-MIN." (PMID 28765560, 2017).
pancreatic cancer (1 paper, 2016). "Previous studies showed that targeted degradation of HPK1 in pancreatic cancer by the CUL7/Fbxw8 ubiquitin ligase involves HPK1 autophosphorylation." (PMID 27023625, 2016).
tumor (6 papers, 2019 to 2025). "IHC staining of xenograft tumor samples was also showed that FBXW8 expression is significantly higher in tumor tissues of mice injected with HCT116 (uc.77-) than in control vector tumors." (PMID 34094975, 2021). "FBXW8 forms a functional E3 ligase complex with cullin 7 to exert a tumor suppressive role." (PMID 30341246, 2019). "FBXW8 has been shown to be able to bind cullin protein 7 (CUL7), which exerts both tumor promotion and suppression in a context-dependent manner." (PMID 40375984, 2025). "Several F‐box containing proteins have been characterized either as tumor suppressors (FBXW8, FBXL3, FBXW8, FBXL3, FBXO1, FBXO4, and FBXO18) or as oncogenes (FBXO5, FBXO9, and SKP2)." (PMID 33822486, 2021).
cancer (5 papers, 2006 to 2022). A tumor composed of atypical neoplastic, often pleomorphic cells that invade other tissues. "The expression level of FBXW8 is a genomic feature of LC 1, which is interesting since this gene is known to play an essential role in cancer cell proliferation." (PMID 31136571, 2019). "In direct contrast, siRNA mediated knockdown of FBXW8 complexes inhibited the proliferation of cancer cell lines." (PMID 17407548, 2007). "It is also possible that while the loss of SCFFBX4-αB crystallin allows the accumulation of cyclin D1 during cancer development, the continued expression of FBXW8 is required to maintain levels below the threshold required to repress DNA replication." (PMID 17407548, 2007). "We have also demonstrated that ERK/MAPK-mediated cyclin D1 degradation through FBXW8 is required for proliferation of cancer cells." (PMID 17205132, 2006). "Studies have shown that Fbxw8 is involved in cancer cell growth via proteolysis." (PMID 33130829, 2020). "We concluded that cyclin D1 levels are regulated by FBXW8 in the cancer cells tested here." (PMID 17205132, 2006). "To test this hypothesis, we determined the subcellular localizations of FBXW8 and cyclin D1 during the cell cycle in cancer cells." (PMID 17205132, 2006). "Therefore, dysregulation of Fbxw8 or Fbxw11 might be an effective therapeutic approach for CUL7-related cancers." (PMID 33130829, 2020). "Thus, FBXW8 plays an essential role in cancer cell proliferation through proteolysis of cyclin D1." (PMID 17205132, 2006). "The siRNA mediated knockdown of CUL1, CUL7 and FBXW8 in HCT116, SW480, U-2 OS and T98 cancer cell lines resulted in the mainly cytoplasmic accumulation of T286 phosphorylated cyclin D1." (PMID 17407548, 2007). "Unlike SCFFBX4-αB crystallin, the FBXW8 complex is clearly expressed in various cancer cell lines." (PMID 17407548, 2007).
infection (1 paper, 2024). The state of being infected such as from the introduction of a foreign agent such as serum, vaccine, antigenic substance or organism. "The mRNA levels of FBXW8 were downregulated in PDCoV-infected cells at 6 hours post-infection (hpi), but significantly upregulated in PDCoV-infected cells at 36 hpi, compared to the levels in uninfected cells." (PMID 39624099, 2024). "However, PDCoV infection induced FBXW8 expression to suppress virus replication via activating the NF-κB signaling axis in the later infection stage." (PMID 39624099, 2024).
FBXW8 also shares sentences with these, for which no sentence is quoted: gastric cancer (1 paper); Insulin resistance (1); Obesity (1).